DAB2 (DAB adaptor protein 2)
Diseases named in the same sentence as DAB2 in open-access papers (continued):
Sharing a sentence is not in itself a finding about the gene and the disease.
type 2 diabetes mellitus (4 papers, 2013 to 2025). A type of diabetes mellitus that is characterized by insulin resistance or desensitization and increased blood glucose levels. "More intriguingly, and only recently, polymorphisms in the Dab2 gene have been associated with type 2 diabetes mellitus in a population-based study." (PMID 39846251, 2025). "Inhibition of Dab2 expression likely underlies the compromised angiogenic function in ECs exposed to hyperglycemia in diabetes mellitus." (PMID 39846251, 2025). "They found 128 SNPs, some of which are located at the Dab2 gene locus, that were associated with incident diabetes." (PMID 37361044, 2023). "Although the precise involvement of Dab2 in diabetes remains to be addressed, Dab2 appears to be involved in regulating blood glucose metabolism; its deficiency, at least in myeloid cells, has been implicated in compromised glucose tolerance in mice." (PMID 39846251, 2025). "The present study was designed to dissect the potential involvement of Dab2 in regulating VEGF signaling during angiogenesis in the context of wound healing in diabetes." (PMID 39846251, 2025). "In our study, the molecular underpinnings of endothelial dysfunction in diabetes are investigated, focusing on the roles of disabled-2 (Dab2) and Forkhead box M1 (FOXM1) in VEGF receptor 2 (VEGFR2) signaling and endothelial cell function." (PMID 39846251, 2025). "Our observations here provide important insights into the precise involvement of the highly conserved endocytic adaptor protein, Dab2, and its transcriptional regulation during wound-induced angiogenesis in diabetes." (PMID 39846251, 2025). "In our quest to investigate the involvement of endocytic adaptor proteins in mitigating aspects of diabetes, we identified Dab2 via our bulk RNA-sequencing analysis of hyperglycemic ECs as one of the downregulated genes." (PMID 39846251, 2025). "As a candidate gene for dyslipidemia, Dab2 is also involved in the development of type 2 diabetes mellitus(T2DM)." (PMID 37361044, 2023). "At the same time, the molecular mechanisms underlying Dab2-mediated angiogenesis, particularly in the context of wound healing in diabetes, are not clear." (PMID 39846251, 2025). "This approach revealed that in diabetic mice, the angiogenic blood vessels within the VEGFA-infused Matrigel exhibited a notable decrease in Dab2 levels compared with those in the WT mice, indicating the impact of diabetes on Dab2 expression and its potential role in angiogenesis." (PMID 39846251, 2025). "FOXM1 is downregulated in diabetes and regulates Dab2 transcription." (PMID 39846251, 2025). "We show the endocytic adaptor Dab2 plays a critical role in blood vessel formation in diabetes, which may lead to new treatments for wound healing." (PMID 39846251, 2025). "Diabetes and high-glucose treatment in ECs lead to the downregulation of Dab2." (PMID 39846251, 2025). "Because of the lack of information about the precise role of Dab2 in diabetes, we went on to develop an EC-specific Dab2-deficient mouse model to examine the effects of Dab2 deletion on angiogenesis in diabetic conditions." (PMID 39846251, 2025). "Although previous studies acknowledge the pivotal role of FOXM1 in diabetes-related cellular functions and β cell proliferation, our study delves into the mechanistic interaction between FOXM1 and Dab2 within the context of ECs and angiogenesis during diabetic wound healing." (PMID 39846251, 2025). "By injecting Dab2 mRNA encapsulated in lipid nanoparticles (LNPs), or using the FOXM1 inhibitor FDI-6, wound healing was significantly enhanced through increased angiogenesis, which could lay the foundation for the development of novel therapies to enhance angiogenesis in diabetes." (PMID 39846251, 2025).
urothelial carcinoma of the bladder (4 papers, 2020 to 2023). "Evidence shows that proteins such as Dab2 play a significant role in aggressive human urothelial carcinoma of the bladder." (PMID 35167594, 2022). "This is consistent with a study in urothelial carcinoma of the bladder, where stromal DAB2 but not epithelial DAB2 was associated with reduced PFS." (PMID 37815603, 2023). "However, a number of contrary studies suggested that DAB2 promotes tumor invasion in urothelial carcinoma of the bladder (UCB)." (PMID 31968685, 2020).
choriocarcinoma (3 papers, 2013 to 2025). An aggressive malignant tumor arising from trophoblastic cells. "A decreased expression of DAB2 has been demonstrated in several cancers including ovarian, breast, prostate, oesophagus, urinary bladder, colon and choriocarcinoma." (PMID 24194935, 2013). "Choriocarcinoma is associated with MARCKS, DAB2, ENPEP, and TIMP1." (PMID 40565366, 2025).
dyslipidemia (3 papers, 2020 to 2023). "The DAB2 gene was differentially overexpressed in periodontitis and dyslipidemia." (PMID 36233348, 2022). "On the DL-P vs. H comparison, which evaluated the effect of the dyslipidemia and periodontitis, the qPCR confirmed that the HLADRB4 and CD47 (CD47 molecule) genes were upregulated in H, while the DAB2 (DAB adaptor protein 2) gene was downregulated in H." (PMID 32424199, 2020).
lung adenocarcinoma (3 papers, 2018 to 2023). A carcinoma that arises from the lung and is characterized by the presence of malignant glandular epithelial cells. "On the other hand, miR-134-5p was reported to promote metastasis and chemoresistance by targeting DAB2 in stage I lung adenocarcinoma." (PMID 34299277, 2021). "This study indicates that DAB2 and Intelectin-1 are novel positive immunohistochemical markers of epithelioid MM, and should allow for its differentiation from lung adenocarcinoma." (PMID 29538329, 2018). "In contrast, miR-134-5p accelerated lung adenocarcinoma metastasis via targeting DAB2." (PMID 38030848, 2023). "A recent study has demonstrated that the positive rates of DAB2 and Intelectin-1 (INLT1) expression were 80% and 76% in epithelioid MM, and 3% and 0% in lung adenocarcinoma, respectively." (PMID 29538329, 2018).
mastitis (3 papers, 2017 to 2022). Inflammation of breast tissue during lactation or postpartum due to an obstructed duct or infection. "Some of the highly connected genes in the purple module have previously been related to mastitis development including NFKBIZ, NFKBIA, CXCL2, GRO1, CXCL3, LPIN1, and DAB2." (PMID 32754201, 2020).
pancreatic cancer (3 papers, 2019 to 2023). "The goal of this study was to investigate the expression of Dab2 during different stages of pancreatic cancer and to investigate if loss of Dab2 expression correlates with EMT and/or the CSC phenotype." (PMID 31101868, 2019). "Together, these results suggest that loss of Dab2 in pancreatic cancer may lead to cooperation between the MAPK and TGFβ signaling pathways required for stable EMT, regardless of the mutational status of K-Ras." (PMID 31101868, 2019). "In addition, decreased Dab2 mRNA expression was shown in early stage pancreatic cancer where loss of Dab2 expression may be mediated in part by promoter methylation." (PMID 31101868, 2019). "A small study in pancreatic cancer found DAB2 expression was enhanced in tumour versus normal pancreatic tissues." (PMID 36614139, 2022). "Downregulation of Dab2 in pancreatic cancer cell lines led to altered gene expression patterns indicative of EMT and upregulation of cancer stem cell-specific markers." (PMID 31101868, 2019). "Downregulation of Dab2 expression in pancreatic cancer cell lines was found to trigger induction of genes characteristic of EMT and the CSC phenotype, while overexpression of Dab2 in the Panc1 cell line blocked the process of TGFβ-stimulated EMT." (PMID 31101868, 2019). "Dab2 mRNA levels were found to be highest in normal pancreatic tissue, while mean Dab2 expression levels were significantly decreased in pancreatic cancer stages I, III, and metastatic tumor samples (p < 0.05)." (PMID 31101868, 2019). "In pancreatic tumors or cell lines which harbor oncogenic K-Ras, such as the Panc1 cell line, downregulation of Dab2 expression would provide the activation of the TGFβ signaling pathway." (PMID 31101868, 2019). "Determination of the mechanism for decreased expression of Dab2 in pancreatic cancer and whether methylation is a significant factor requires further analysis in additional tumor samples." (PMID 31101868, 2019). "Results presented in this study show that Dab2 may act as a tumor suppressor in pancreatic cancer by inhibition of TGFβ-stimulated EMT and the CSC phenotype." (PMID 31101868, 2019). "Methylation of the Dab2 gene promoter was demonstrated in Stage I PDAC tumors and in the MiaPaCa2 cell line, suggesting that promoter methylation may silence Dab2 expression early in pancreatic cancer progression." (PMID 31101868, 2019). "Whether the primary role of Dab2 as a tumor suppressor in pancreatic cancer is through a direct effect on the tumor cells themselves or through effects on the tumor microenvironment remains to be determined." (PMID 31101868, 2019). "In summary, these results show that decreased Dab2 mRNA levels are observed in pancreatic cancer as compared to normal pancreatic tissue and may serve as a prognostic marker for cancer progression." (PMID 31101868, 2019). "However, Dab2 may play an indirect role as a tumor suppressor in pancreatic cancer by affecting TGFβ levels within the tumor microenvironment through its modulation of the cell-surface expression of the TGFβ receptors." (PMID 31101868, 2019). "As activation of the TGFβ signaling pathway has been linked to metastasis, chemoresistance, and poor prognosis, a further understanding of the role and regulation of Dab2 during pancreatic cancer progression may identify novel targets for therapeutic intervention." (PMID 31101868, 2019). "In pancreatic cancer cell lines (COLO357 and PANC), DAB2 knock down enhanced TGFβ-mediated EMT through reduced E-cadherin and enhanced Snail, Slug and N-cadherin expression." (PMID 36614139, 2022). "However, the role of Dab2 in pancreatic cancer development and progression remains unclear." (PMID 31101868, 2019). "Pancreatic cancer cell lines that express wild-type K-Ras, the COLO357 and BxPC3 cell lines, were found to exhibit higher protein and mRNA levels of Dab2 compared to AsPC1, Panc1 and MiaPaCa2 cell lines, which express a mutant form of the K-Ras protein." (PMID 31101868, 2019).
pancreatic cancer (continued). "In this study, decreased expression of Dab2 in COLO357 and Panc1 pancreatic cancer cell lines altered the expression of genes involved in the EMT/CSC phenotype mediated by TGFβ." (PMID 31101868, 2019). "Research into pancreatic cancer found no DAB2 expression in normal pancreatic tissues (n = 5), however in 7/8 pancreatic cancer tissues had low or high DAB2 expression." (PMID 36614139, 2022). "We were unable to interrogate the difference in mRNA Dab2 levels between normal pancreatic tissue and the various stages or grades of pancreatic cancer, as normal pancreatic tissue was not included in this database." (PMID 31101868, 2019). "In addition, Dab2 promoter methylation was observed in 1/5 of metastatic pancreatic tumor samples, while no Dab2 promoter methylation was seen in Stage II or Stage III tumor samples." (PMID 31101868, 2019).
dysplasia (2 papers, 2017 to 2024). A usually neoplastic transformation of the cell, associated with altered architectural tissue patterns. "This is likely associated with the uterine dysplasias that develop in these mice, and indicates that DAB2 plays an important role in maintaining epithelial stability in many parts of the female reproductive tract." (PMID 29196616, 2017). "In this study, we also analysed the DAB2 expression in H pylori-positive atrophic gastritis, intestinal metaplasia, and dysplasia in the multi-step pathological processes of Correa’s cascade, and found that DAB2 expression increased with disease progression." (PMID 38481347, 2024). "Meanwhile, we detected the co-expression of DAB2 and active-YAP1 in patients with atrophic gastritis, intestinal metaplasia, and dysplasia." (PMID 38481347, 2024).
head and neck cancer (2 papers, 2014 to 2016). A primary or metastatic malignant neoplasm affecting the head and neck. "One study found that Dab2 loss in head and neck cancer compromised the tumor suppressor function of TGF-beta, while enabling its tumor-promoting activities, and concluded that Dab2 is a molecular switch for TGF-beta from a tumor suppressor to a promoter." (PMID 25360623, 2014).
Hypercholesterolemia (2 papers, 2019 to 2024). An increased concentration of cholesterol in the blood.
Hyperglycemia (2 papers, 2023 to 2025). An increased concentration of glucose in the blood. "They found that hyperglycemia increased Dab2 expression in cardiomyocytes." (PMID 37361044, 2023). "In contrast, inhibition of Dab2 mRNA and protein expression can reverse hyperglycemia." (PMID 37361044, 2023).
liver diseases (2 papers, 2017 to 2020). "Targeting drugs inhibiting Dab2 expression might provide a novel therapy that improves LSEC homeostasis and blocks angiogenesis associated with multiple liver diseases." (PMID 29044176, 2017).
Lung Diseases (2 papers, 2019 to 2022). "The top predicted genes were DAB2 and PTENP1 and the top ranked diseases were Lung Diseases and Ovary Syndrome." (PMID 31345171, 2019). "Based on pathway enrichment analysis, genes altered in BPD blood cells were mainly enriched in cell cycle regulation and arrest (e.g., PPP2CA, RBL2, CENPU, CCNY, CDK6) and pulmonary disorder and developmental disorders (e.g., AGER, ITGA6, CA4, BACH2, IGFBP2, BMPR2, SKI, DAB2)." (PMID 35484630, 2022).
multiple sclerosis (2 papers, 2013 to 2015). A progressive autoimmune disorder affecting the central nervous system resulting in demyelination. "Together, these results suggest that endogenous Dab2 exacerbates central nervous system inflammation, potentially acting to up-regulate reactive oxygen species expression in macrophages and microglia, and that it is of potential pathogenic relevance in Multiple Sclerosis." (PMID 24252604, 2013). "In humans, Dab2 was up-regulated in a microarray study of autopsy specimens in multiple sclerosis lesions." (PMID 25822971, 2015). "In Multiple Sclerosis, we show that Dab2 is highly expressed in macrophages in the early acute lesion, but that its expression is diminished in late acute lesions and almost absent in chronic MS lesions." (PMID 24252604, 2013). "We further demonstrate that Dab2 is expressed at the protein level by macrophages in early acute human multiple sclerosis lesions and that this correlates with axonal injury." (PMID 24252604, 2013). "We report that Dab2 is up-regulated in lesional macrophages/microglia in the spinal cord in murine experimental autoimmune encephalomyelitis, a model of multiple sclerosis." (PMID 24252604, 2013).
non-small cell lung carcinoma (2 papers, 2022 to 2023). A group of at least three distinct histological types of lung cancer, including non-small cell squamous cell carcinoma, adenocarcinoma, and large cell carcinoma. "Furthermore, it has been shown that X radiation can induce DAB2 in hypermethylated non-small-cell lung cancer by up-regulating DNA methyl transferase (DNMT), the enzyme that demethylates the promoter region of DAB2." (PMID 37510211, 2023). "Low DAB2 gene expression was also associated with reduced OS and PFS in patients with non-small cell lung carcinoma (NSCLC)." (PMID 36614139, 2022).
Obesity (2 papers, 2016 to 2021). Accumulation of substantial excess body fat. "Nevertheless, we observed that the Dab2 null mice are resistant to high fat diet-induced obesity, and uncovered its role in controlling the differentiation of a pre-adipocyte population." (PMID 27779214, 2016). "First, the regulation of adipocyte cell number has a dominating role in controlling obesity in juvenile animals, since the lean Dab2 null mice have fewer adipocytes despite a greatly increased cell size." (PMID 27779214, 2016). "The current investigation of a striking obesity resistant phenotype of Dab2 null mice revealed the mechanism of the Ras/MAPK pathway regulation in the differentiation and cell numerical expansion of adipocytes in mice." (PMID 27779214, 2016).
pancreatic ductal adenocarcinoma (2 papers, 2019 to 2023). An infiltrating adenocarcinoma that arises from the epithelial cells of the pancreas. "Many of those genes were related to various kinds of neoplasia progression (Tpx2, Id3, Top2a, Dab2, Mecom, Nrp1107–112), including pancreatic ductal adenocarcinoma, or pancreatitis (Gsn113)." (PMID 37689751, 2023).
periodontitis (2 papers, 2020 to 2022). An acute or chronic inflammatory process that affects the tissues that surround and support the teeth. "In subjects with DL plus periodontitis versus HS, three DEG were confirmed (DAB2, CD47, and HLADRB4), and in the comparison between subjects with periodontitis alone versus HS: the IGHG3 gen (IGHDL-P) was upregulated, and the ITGB2 and HLADRB4 genes were downregulated." (PMID 36233348, 2022).
transitional carcinoma (2 papers, 2021 to 2022). "Another mechanism for regulating DAB2 expression is through the GATA6 transcription factor, which has been shown to directly enhance DAB2 expression in transitional cell carcinomas (TCC)." (PMID 36614139, 2022).
adenoma (1 paper, 2021). A neoplasm arising from the epithelium. "Furthermore, two-thirds of APAs exhibited positive immunohistochemical staining of G Protein Activated Inward Rectifier Potassium Channel 4 (GIRK4) and Dab2, both markers of the ZG, rendering these possible markers for the distinction of APAs from non-functioning adenomas." (PMID 34771744, 2021).
alopecia (1 paper, 2022). Hair loss usually from the scalp. "In this study, DAB2 was identified as a target protein associated with three compounds involved in 20 main medicinal herbs for alopecia treatment." (PMID 35181715, 2022). "Therefore, the main medicinal herbs may exert an effect on alopecia via modulation of DAB2, leading to the inhibition of Wnt signaling." (PMID 35181715, 2022).
autism (1 paper, 2014). Persistent deficits in social interaction and communication and interaction as well as a markedly restricted repertoire of activity and interest as well as repetitive patterns of behavior. "The region of maternal association on chromosome 5 falls between the PTGER4 and DAB2 genes, in a region previously implicated in autism and ADHD." (PMID 24571439, 2014).
autoimmune disease (1 paper, 2020). A disorder resulting from loss of function or tissue destruction of an organ or multiple organs, arising from humoral or cellular immune responses of the individual to their own tissue constituents. "Therefore, the precise role of DAB2 in inflammatory and autoimmune diseases still remains poorly characterized." (PMID 33178208, 2020). "The reported findings suggest that DAB2 repression in DCs may indeed contribute to pathogenesis of autoimmune diseases." (PMID 33178208, 2020).
Autoimmunity (1 paper, 2016). The occurrence of an immune reaction against the organism's own cells or tissues. "However, mice with Dab2 deletion in Treg cells are healthy in appearance and do not show phenotypes related to autoimmunity defects even at 1 year of age, indicating that the Dab2 is dispensable for Treg cells in maintaining T cell tolerance." (PMID 27933291, 2016).